INS (insulin)
Diseases named in the same sentence as INS in open-access papers (continued):
Sharing a sentence is not in itself a finding about the gene and the disease.
diabetes (continued). "Type 2 diabetes mellitus (T2DM), the most common form of diabetes, is characterized by insulin resistance, particularly in adipose tissue, skeletal muscle, and liver cells, alongside impaired insulin secretion from pancreatic β cells." (PMID 40742490, 2025). "Type 2 diabetes mellitus (T2DM), which accounts for 90% of all diabetes cases, is primarily characterized by defects in insulin secretion from pancreatic β-cells and an inability of insulin-sensitive tissues to respond appropriately to insulin." (PMID 40761848, 2025). "We found that ≈38% of participants with diabetes in our cohort were not prescribed insulin or oral antihyperglycaemics." (PMID 38964833, 2025). "Diabetes mellitus (DM), a class of metabolic diseases characterized by an irregular increase in blood glucose levels, is characterized by an imbalance in the production of insulin or insensitivity to the hormone's effects on the transmission of cellular receptor signals." (PMID 40641385, 2025). "Seven patients with type 2 diabetes mellitus were treated by diet/lifestyle measures only, and one single patient with diabetes mellitus type 1 did not require insulin treatment after having received a pancreas transplant a few years earlier." (PMID 40564000, 2025). "In 2005, the Diabetes Immunology Society established three criteria for the diagnosis of LADA: onset of the disease after the age of 30 years, presence of any antibody against the islets, and insulin independence for at least six months after diagnosis." (PMID 40995267, 2025). "Currently, no single definitive biomarker reliably assesses insulin dysregulation for diagnosing diabetes before its onset." (PMID 40244147, 2025). "A recent paper in Diabetes Care noted strengths and inaccuracies of the recent GPT-4 model developed by OpenAI when asked questions on diet/exercise, glycemic management, and insulin storage and administration in adult patients." (PMID 41202176, 2025). "Diabetes is a serious, chronic condition where the body either cannot produce sufficient insulin, produces no insulin at all, or is unable to effectively use the insulin it produces." (PMID 40162316, 2025). "Unlike traditional medication such as metformin and insulin used for treating diabetes that focuses on enhancing insulin secretion or sensitivity, SGLT2i targets the kidneys." (PMID 41446634, 2025). "All 8 probands were treated with insulin since diagnosis (median dose = 1.1 units/kg/day, range 0.3 to 2), with no diabetes remission periods reported." (PMID 40887432, 2025). "Diabetes mellitus is a non-communicable metabolic disorder characterized by the inability to produce or effectively utilize insulin." (PMID 40724270, 2025). "For example, the Diabetes Medication Choice decision aid, developed in the US, is for patients who are not (yet) using insulin and have multiple treatment options to consider." (PMID 40121397, 2025). "In conclusion, emodin demonstrates remarkable potential in the treatment of diabetes, it could effectively reducing FBG, 2hPG (IPGTT/ OGTT), IPITT, TC, TG, insulin levels and body weight in T2DM animal models." (PMID 40386230, 2025). "A meta‐analysis of 22 randomised controlled trials concluded that fibre intake at 10 g per day for 8 weeks improved HbA1c, fasting insulin, HOMA‐IR and fasting glucose levels in non‐pregnant people with type 2 diabetes and should be considered alongside other treatment methods for diabetes." (PMID 39473074, 2025). "Diabetes duration >10 years yielded an AUC of 0.62 (95% CI: 0.56–0.68; p = 0.004), while insulin use (any vs. none) showed an AUC of 0.66 (95% CI: 0.60–0.72; p < 0.001)." (PMID 41008733, 2025). "The level of placental histone methylation is higher in neonates with no diabetes exposure, lower in neonates with maternal diabetes exclusively under diet modifications and lower in neonates with maternal diabetes under insulin therapy." (PMID 41007128, 2025).
diabetes (continued). "All strokes occurred in hypertensive and insulin-requiring patients with diabetes; none led to SGLT2i discontinuation." (PMID 40225369, 2025). "Unlike fully closed‐loop systems, the person with diabetes is still required to manually program insulin boluses with meals." (PMID 39432570, 2025). "Firstly, regarding the effects of mVOCs on the endocrine system, previous studies have found positive associations between low-level exposure to VOCs, especially HPMMA, and diabetes, insulin resistance (TyG index), fasting glucose (FPG), glycosylated hemoglobin (HbA1c), and insulin levels." (PMID 40735206, 2025). "When the mother has diabetes, the blood sugar level is high also in the foetus and the foetal beta cells are matured early and produce a lot of insulin which normally is not the case." (PMID 38798081, 2025). "Type 1 Diabetes (T1D), formerly known as juvenile or insulin-dependent diabetes mellitus (DM), is a chronic condition in which the pancreas produces little to no insulin." (PMID 40430489, 2025). "In terms of diabetes management, most of the patients were treated with non-insulin antidiabetic drugs, 30.5% were under treatment with insulin, and 12.4% received a combination of the two." (PMID 40137422, 2025). "Those who were diet-controlled or receiving insulin management (not metformin) showed higher rates of spontaneous pretreatment rupture than those on noninsulin medications (and those without diabetes)." (PMID 40759177, 2025). "The results from our study in animals with fully developed diabetes did not confirm the anti-diabetic and insulin-sensitizing effect of QCT, and therefore we believe that preventive treatment would be more effective." (PMID 39576482, 2025). "Overall, the expert HCPs participating in the Delphi Survey expressed considerable confidence that primary care teams will adapt to managing insulin‐treated people with T2D using CGM (71.4%) and that this will reduce diabetes‐related healthcare costs for this participant group (94.3%)." (PMID 39676327, 2025). "Together, these findings suggest that neither reductions in total β cell numbers nor defects in insulin synthesis or processing are major contributors to the diabetes that develops in Gnas knockouts." (PMID 40526441, 2025). "Our QI efforts allowed for increased uptake of insulin pump therapy within 1 year of diabetes diagnosis without contributing to DKA events." (PMID 40110444, 2025). "Finally, for youth who adopt diabetes technologies, such as CGM and automated insulin delivery systems, the inclusion of diabetes device data would likely significantly augment our model’s predictions." (PMID 40997334, 2025). "AD patients with concurrent diabetes or insulin resistance could be prime candidates, as GLP-1RAs improve neuronal insulin signaling." (PMID 41226780, 2025). "Here, 3-dimensional (3D) analyses of pancreata from control persons without diabetes (ND) revealed heretofore underappreciated frequencies (approximately 50%) of insulin-positive (INS+) glucagon-negative (GCG-) islets." (PMID 40502779, 2025). "By contrast, the absence of any DCM cases in hyperthyroid participants with insulin-treated diabetes—while intriguing—should be cautiously interpreted due to limited subgroup size." (PMID 41153651, 2025). "Thus, in the context of diabetes, zinc-dependent drug targeting to β-cells could be improved by pharmacologically increasing β-cell zinc with a compound like GR-46611 and/or through insulin therapy to promote β-cell rest, boost insulin content and thus, zinc levels." (PMID 40885390, 2025). "The association between income and severe hypoglycemia was consistently greater in men, individuals not using insulin, those without chronic kidney disease, and those with a shorter duration of diabetes." (PMID 40455444, 2025).
diabetes (continued). "However, HOMA-IR, which is based on fasting glucose and insulin levels, may be influenced by exogenous insulin administration, particularly in diabetes mellitus (DM) individuals, potentially reducing its accuracy in certain populations." (PMID 40979948, 2025). "This is the first study to evaluate the role of skeletal muscle gene expression ofglucose transporters and insulin signaling genes in critically ill patients withstress-induced hyperglycemia, with or without diabetes." (PMID 40179269, 2025). "Individuals without diabetes but with insulin resistance (IR) exhibited elevated fasting insulin, fasting C-peptide, HbA1C, BMI and tend to be older compared to their insulin-sensitive (IS) counterparts." (PMID 40421243, 2025). "The proportion of poor sleep health was higher in all patients with diabetes without regard to their therapeutic regimens i.e., insulin, insulin secretagogues, or both medications." (PMID 40357213, 2025). "Finally, α-Klotho can regulate energy metabolism and partially inhibit the insulin/IGF-1 signaling pathway, thereby delaying cell senescence and providing a theoretical basis for its potential role in the development of diabetes." (PMID 41438297, 2025). "The evidence available is discordant, with reports of no change in insulin requirements, an increase in insulin requirements and two case reports describing complete remission of diabetes in patients with long‐standing insulin‐dependent diabetes." (PMID 40664615, 2025). "Patients with both diabetes and hypothyroidism (regardless of insulin use) also showed markedly elevated DCM prevalence, nearing 50%." (PMID 41153651, 2025). "Three months after diabetes induction, mice exhibited slightly lower insulin levels (p < 0.4458) compared to controls, with no diet effect observed." (PMID 40141119, 2025). "48.7% believed that taking insulin means that they had failed to manage their diabetes with diet and tablets.71.4% believed that taking insulin means their diabetes has become much worse." (PMID 40336418, 2025). "Women with hyperglycemia and diabetes-related autoimmunity display a peculiar clinical profile: they usually have a normal pre-pregnancy BMI, low insulin resistance, and require insulin therapy more often than antibody-negative patients with hyperglycemia." (PMID 41020242, 2025). "Simple routine insulin injection is not enough to control and treat diabetes, and so researchers are studying the application of a traditional Chinese medicine for diabetes." (PMID 41463300, 2025). "Diabetes mellitus (DM) is a metabolic disease characterized by chronic hyperglycemia due to a lack of insulin secretion and decreased insulin efficiency." (PMID 41036937, 2025). "The study results indicate that insulin levels as well as the prevalence rates of hyperinsulinemia and IR are on the rise among adolescents without diabetes/prediabetes over the last two decades." (PMID 40365140, 2025). "Insulin secretion is suppressed under high blood sugar levels in those without diabetes, which worsens myopia by thickening the lens and shifting the anterior pole forward." (PMID 39861390, 2025). "Although insulin is routinely indicated in many dialysis units for glycemic control in patients with diabetes, CP is not included as part of their regular monitoring." (PMID 40978759, 2025). "This testing is recommended when classification of diabetes remains uncertain, such as in adults suspected of having T1D or have rapid insulin requirement but with negative pancreatic autoantibodies." (PMID 39797595, 2025). "The common type of diabetes is type 2 diabetes, which appears when the body does not produce enough insulin or becomes resistant to it." (PMID 41149596, 2025). "If this compensatory hyperinsulinemia persists for a long time, it causes pancreatic β-cell function to gradually decline, reduces insulin secretion, and fails to effectively control blood sugar levels, eventually leading to diabetes." (PMID 40842495, 2025).
diabetes (continued). "TMAO levels are elevated in T2D and predictive of future diabetes, and markedly suppressing its formation through genetic or pharmacological inhibition of the hepatic FMO3 enzyme has been proposed to improve insulin secretion and glycemic control in diabetic mice." (PMID 40871736, 2025). "The PPP, meanwhile, plays a dual role in diabetes: overactivation promotes oxidative stress and inflammation through NADPH oxidases, while insufficient flux impairs β-cell NADPH production, compromising glutathione recycling and insulin secretion." (PMID 41441003, 2025). "In Japan, where individuals aged 65 years and older account for over 70% of those with diabetes, a distinct non-obese phenotype with impaired insulin secretion is commonly observed." (PMID 40607140, 2025). "The total cholesterol and LDL-C did not change much, but diabetes, insulin, and hsCRP increased several-fold with increasing BMI, and that was true even after adjusting data for age." (PMID 40077610, 2025). "Advanced diabetes technologies such as continuous glucose monitoring (CGM), continuous subcutaneous insulin infusion (insulin pumps [CSII]), and glucometers alongside insulin access represent the criterion standard for managing type 1 diabetes (T1D) in children." (PMID 40864470, 2025). "This mode of action presents an interesting strategy to target hyperglycemia, since established diabetes therapies do not target insulin-independent glucose uptake via GLUT1." (PMID 40818962, 2025). "Participants identified the constant challenge and balancing act of managing diabetes and insulin therapy; as one participant put it: ‘It's just not a clear cut and dried...do A and B will result’ (P4)." (PMID 41358572, 2025). "Unfortunately, steroids have been shown to lead to increased hyperglycaemia and, subsequently, diabetes by reducing insulin sensitivity and impairing the function of the glucose transporter type 4 (GLUT4), with a consequent reduction in insulin-stimulated glucose uptake." (PMID 41567924, 2025). "If possible, glycemic control strategies should aim for the remission of diabetes, yet without stimulating hyperinsulinemia, but rather due sensitization of insulin target tissues." (PMID 40277890, 2025). "In total, 8.4% (n=14) reported type 1 diabetes, 66.9% (n=111) reported type 2 diabetes, and 24.7% (n=41) did not know their diabetes type; 50% (n=83) reported using insulin for diabetes management." (PMID 40266665, 2025). "Diabetes mellitus is a chronic metabolic disease that occurs when the pancreas does not produce sufficient insulin or when the body cannot effectively utilise the insulin it produces." (PMID 41322821, 2025). "Research indicated an enhancement in insulin sensitivity in mice possessing Fetuin-A deletion genes, demonstrating a negative correlation between Fetuin-A and insulin sensitivity in diabetes." (PMID 40141412, 2025). "A substantial body of literature links alterations in intrarenal insulin signaling to kidney dysfunction in animal models and people with or without diabetes." (PMID 41163811, 2025). "Instances where diabetes mellitus was reported without an explicit specification of insulin dependency were categorized as insulin-independent by default." (PMID 41404107, 2025). "We previously found that individuals with diabetes treated with “non-insulin GLD only” and “insulin and non-insulin GLD” had a lower risk of long-term nursing home stays compared to other recipients of HCS, which aligns with this explanation." (PMID 41350985, 2025). "Currently, exogenous insulin is administered to support most patients with diabetes to overcome the absence of functional pancreatic β-cells." (PMID 40014427, 2025). "We observed a significant difference in resuspending cloudy insulin before use (p = 0.024) and a high frequency of poor knowledge among participants who did not receive training from the diabetes education specialist." (PMID 40376558, 2025).
diabetes (continued). "Three months post-VSG, youth showed significant improvements in weight, body composition, insulin sensitivity and secretion, and glycemic control, with most no longer requiring diabetes medications." (PMID 39911520, 2025). "Her medical history included diabetes managed with insulin but no engagement with an endocrinologist or allied health support." (PMID 39786791, 2025). "Among the most common diabetes mellitus medications, metformin stands out with prescription to 80% of patients, followed by the group comprising SGLT-2 inhibitors (19%), DPP-4 inhibitors (14%), GLP-1 RA (7%) and insulin (8%)." (PMID 39946340, 2025). "In individuals with T2DM, serum putrescine levels are significantly higher compared to those without diabetes, and serum putrescine and spermine levels correlate with glycosylated hemoglobin (HbA1c) and fasting insulin levels, respectively." (PMID 39796620, 2025). "Such devices are not currently routinely integrated into electronic health records (EHR) and are not universally used for all people with diabetes who use insulin; however, researchers are exploring the safety and potential benefits of this approach." (PMID 40696540, 2025). "A total of 59.8% and 67.4% respondents, respectively, also correctly observed that kidneys do not produce insulin and that diabetes cannot be cured." (PMID 41537571, 2025). "The subgroup analysis of diabetes patients revealed no significant disparities across BMI, current HbA1c levels, duration of insulin pump therapy, or insulin dosage." (PMID 40564977, 2025). "In metabolic diseases such as type 2 diabetes mellitus (T2DM) and obesity, BBR has been shown to coordinate responses at multiple molecular levels, restoring metabolic balance, reducing inflammation, and improving insulin sensitivity." (PMID 40710568, 2025). "The integrity of the ER response is critical as a molecular mechanism for alleviating stress during insulin biosynthesis and processing, regardless of the diabetes subtype." (PMID 41234236, 2025). "Associations of Long COVID documentation with clinical outcomes among Veterans with diabetes who do and do not use insulin, n = 1,896,080." (PMID 40403025, 2025). "SPARC also causes insulin resistance and is positively correlated with BMI, waist circumference, fasting blood glucose, and fasting insulin; therefore, SPARC may be a key participant in obesity and type-2 diabetes mellitus." (PMID 38977622, 2025). "This study provides a novel contribution to the literature by reporting the experiences and challenges faced by 10 older adults with diabetes, with or without frailty, when managing insulin during a surgical hospital admission." (PMID 41358572, 2025). "Firstly, PA helps to control blood glucose levels, improve insulin sensitivity, and increase insulin secretion, thereby maintaining the normal functioning of the brain and reducing the negative effects of diabetes and prediabetes on cognitive function." (PMID 40630407, 2025). "A group of adults with insulin-requiring diabetes from the same FQHCs who did not receive the DSC intervention (n = 363) was used for comparison." (PMID 40678170, 2025). "All participants undergoing elective procedures, rather than emergency admissions, had their diabetes and insulin treatment acknowledged in consultations before surgery." (PMID 41358572, 2025). "Timeline of current episode: February 2015: the patient was diagnosed with type 2 diabetes mellitus, managed with insulin, and hypertension, which was not well-controlled on medication." (PMID 41393183, 2025). "Apart from Patient 12, the other four patients had elevated blood sugar levels and no increase in insulin secretion, which is similar to typical type 1 diabetes mellitus (T1DM) with positive diabetes autoantibody." (PMID 40303944, 2025).